ACE (angiotensin I converting enzyme)
Diseases named in the same sentence as ACE in open-access papers (continued):
Sharing a sentence is not in itself a finding about the gene and the disease.
diabetes (1,242 papers, 2001 to 2026). "According to the literature, we can conclude that the greatest importance of determining ACE I/D gene polymorphism lies in the management of chronic complications in patients with diabetes." (PMID 40149592, 2025). "Identified patient risk factors encompass female sex, the presence of diabetes mellitus, compromised baseline renal function, and the administration of angiotensin II receptor blockers (ARBs) or angiotensin-converting enzyme (ACE) inhibitors." (PMID 41303638, 2025). "The observed risk reduction cannot be attributed to SGLT2i therapy alone but rather represents the cumulative effect of comprehensive diabetes and cardiovascular risk management, including the documented intensification of statin and ACE inhibitor/ARB therapy." (PMID 41010570, 2025). "ACE inhibitors and ARBs commonly have beneficial effects on patients with CV risk factors (hypertension, diabetes), with heart diseases (HF, CAD, MI) and CKD." (PMID 39342254, 2024). "The D allele of the ACE gene was also found to be a strong and independent risk factor for coronary artery disease in patients with non-insulin-dependent diabetes mellitus." (PMID 38279313, 2024). "In cardiovascular disease patients, the ACE I/I genotype and I allele were associated with increased circulating glucose levels and hence a 2-fold increased risk of diabetes." (PMID 37238156, 2023). "The Kidney Disease Improving Global Outcomes (KDIGO) as well as the American Diabetes Association (ADA) guidelines have recommended the use of ACE inhibitors and ARBs for patients with DKD to reduce blood pressure and to achieve ≥30% reduction in albuminuria." (PMID 38068400, 2023). "Recent findings, as well as this research here within, have shown an association between the ACE D allele, diabetes, and the risk of developing cardiovascular disease." (PMID 35741131, 2022). "It has been found that insertion/deletion polymorphism of ACE is common among patients and that deletion of the rs179975 polymorphism of ACE gene was associated with DKD in people with diabetes." (PMID 33976959, 2021). "In this study we investigated the possible relationship between ACE gene I/D polymorphism and diabetes in a group of patients from Saudi Arabia." (PMID 33507688, 2021). "Our results were consistent across all sensitivity analyses, including a more restrictive definition of CKD, a cohort covering a 36-month period, and using the ACC/AHA and American Diabetes Association guidelines to determine ACE-inhibitor/ARB eligibility." (PMID 34401719, 2021). "Although perhexiline, statins and some ACE inhibitors have shown promise in their ability to improve hemodynamic and vasodilator responses in diabetes, there are limitations associated with their use in emergency treatment of cardiovascular disorders." (PMID 32508651, 2020). "The variables set prior to the study were age, gender, BMI, ASA status, diabetes, and if the patients were on any other antihypertensive in addition to ACE inhibitors and their associations with intraoperative hypotension." (PMID 32064194, 2020). "There is scant literature available that predicts diabetes as a risk factor for intraoperative hypotension for hypertensive patients on ACE inhibitors." (PMID 32064194, 2020). "It was concluded in this study that factors affecting ACE 2 expression, such as diabetes and patients on ACE inhibitors, were associated with delayed viral clearance." (PMID 32724306, 2020). "In categorical variables, diabetes mellitus, cerebral infarction, peripheral artery disease, insulin use, ACE inhibitor use, and diuretics use were associated with elevated log-NLR." (PMID 31014150, 2019). "The insertion in ACE I/D polymorphism was a protection factor for the development of DN in individuals with type 2 diabetes mellitus from both East and South Asian origin, and for ESRD in an East Asian population." (PMID 31048445, 2019).
diabetes (continued). "For cardiac ischemia, induction of similar, deleterious renal phenotypes in diabetes by either deficiency in K1 or overexpression of the ACE gene is consistent with kinin bioavailability having a major role in renal protection against hyperglycemia." (PMID 31316987, 2019). "We investigated the possible relationship between ACE gene I/D polymorphism and obesity in Chinese type 2 diabetes mellitus (T2DM) patients." (PMID 28115791, 2016). "ACE inhibitors are seen as more appropriate for first-line use when other high-risk conditions are present, such as diabetes." (PMID 24053215, 2013). "In this study, between elderly hypertensive group, elderly hypertensive with diabetes group and healthy control group, the frequencies of ID and DD genotype in ACE gene, as well as the frequency of D allele, were significantly increased." (PMID 24354906, 2013). "The risk of diabetes increased with diuretics compared to ACE-inhibitors (RR 1.43; 1.12 to 1.83) and CCB (RR 1.27; 1.05 to 1.57)." (PMID 22480336, 2012). "Al-Mallah reported a relative risk of 0.78 (95%CI 0.70-0.88) for the development of diabetes with ACE inhibitors and a relative risk of 0.8 (95%CI 0.75-0.86) for angiotensin receptor blockers versus non-RAS based treatments." (PMID 22230104, 2012). "Diuretics, however, significantly increased the risk of diabetes relative to ACE-inhibitors (RR 1.43; 95% CrI 1.12 to 1.83) and CCB (RR 1.27; 95% CrI 1.05 to 1.57), based on moderate and high quality evidence, respectively." (PMID 22480336, 2012). "Studies have already demonstrated the cost-effectiveness of ARBs and ACE-inhibitors in patients at increased risk of diabetes and heart failure." (PMID 20813031, 2010). "By contrast, oral glucose-lowering medications for diabetes, oestrogens, and ACE inhibitors cause a modest reduction in ADMA." (PMID 21532773, 2010). "ACE inhibitor use is associated with a lower likelihood of a history of cancer and peptic ulcers in patients with diabetes." (PMID 19061507, 2008). "For every 5 to 10 mmHg decrease in systolic blood pressure achieved with diuretics, ARBs, ACE inhibitors, beta-blockers or calcium channel blockers in patients with diabetes, there is a 20% to 30% relative risk reduction in cardiovascular events." (PMID 15461784, 2004). "Furthermore, the ACE genotype has been associated with cardiovascular disease, diabetes, cardiac autonomic neuropathy as part of diabetes progression, COVID-19, and recurrent aphthous stomatitis." (PMID 40367215, 2025). "These factors were underlying CKD, diabetes, and usage of ACE inhibitors." (PMID 40447999, 2025). "The Diabetes Canada 2018 Clinical Practice Guidelines emphasize individualized blood-pressure targets, regular monitoring, and first-line therapies such as ACE inhibitors or ARBs for patients with diabetes, particularly those with albuminuria or cardiovascular risk factors." (PMID 41446498, 2025). "In addition, some medications are recommended across two or more CVD risk factors, such as statin therapy for diabetes and dyslipidemia treatment or ACE inhibitors/angiotensin receptor blockers for diabetes and hypertension treatment." (PMID 39958153, 2025). "Regarding diabetes and metabolic disorders, two studies indicated that genetically proxied ACE inhibitors may lower the risk of type 2 diabetes, while BBs showed an inverse association in both European and East Asian populations." (PMID 39567981, 2024). "Traditionally, angiotensin-converting enzyme (ACE) inhibitors and angiotensin II receptor antagonists (ARBs) have been used to reduce the risk of kidney disease progression and CV complications in individuals with kidney disease and diabetes." (PMID 36719097, 2023). "ACE inhibitors can reduce mortality, myocardial infarction, stroke, and heart failure among patients with left ventricular dysfunction, previous vascular disease, and high-risk diabetes." (PMID 34533690, 2023).
diabetes (continued). "The Kidney Disease Improving Global Outcomes (KDIGO) 2022 guideline as well as the American Diabetes Association 2022 guideline advise using ≥30 mg/day finerenone in patients with albuminuria despite being on a combination of ACE inhibitor and SGLT-2 inhibitor." (PMID 37834846, 2023). "Thus, we aimed to perform a systematic review with meta-analysis to elucidate the relationship between the ACE gene (I/D) polymorphism (rs1799752) and the development and progression of DR in type 2 diabetes mellitus (T2DM) patients." (PMID 37763076, 2023). "In addition, research conducted in South India showed a link between the ACE II genotype and the I allele, which was exacerbated by factors such as smoking and diabetes among patients with IS." (PMID 37034069, 2023). "In addition, the classical RAS driven by ACE has been shown to be associated with a variety of diseases such as chronic heart disease, kidney disease and diabetes." (PMID 36386190, 2022). "Of those physicians who currently prescribe ACE inhibitors/ARBs to low-risk patients, 94% (157/162 endocrinologists and 179/196 PCPs) noted they would increase the dose of ACE inhibitors/ARBs in type 2 diabetes mellitus patients at an increased risk of diabetic kidney disease." (PMID 35913946, 2022). "Because of the important role of RAS in the pathogenesis of cardiovascular, respiratory diseases and diabetes, cross-models of ACE and ACE2 genotypes may exacerbate COVID-19 by causing RAS imbalance through the increase in the increasing ACE/ACE2 ratio." (PMID 35305693, 2022). "Therefore, effective control of blood glucose fluctuations and inhibition of inflammatory hyperexpression in the stage of diabetes can weaken the damage caused by ACE/Ang II in β cells." (PMID 36253996, 2022). "In terms of ACE associated with metabolic-related disorders, a previous study on 90 patients with diabetes reported that urine ACE2 might potentially function as a marker for monitoring the metabolic status, which partially supports the current findings." (PMID 35011591, 2021). "In addition, ACE I/D polymorphism were strongly associated with advanced age, diabetes and ischemic heart disease in COVID-19 patients whereas ACE-II genotype was a protective factor against the development of severe COVID-19." (PMID 34834450, 2021). "A significant univariate association between age; sex; body mass index; smoking; diabetes; cardiovascular, pulmonary, neurological, and kidney diseases; ACE inhibitor therapy; statin intake and an increased risk for complicated clinical stages of COVID-19 at diagnosis was found." (PMID 33001409, 2021). "In addition, ACE I/D polymorphisms were strongly associated with advanced age, diabetes and coronary artery disease in COVID-19 patients whereas ACE-II genotype was a protective factor against the development of severe COVID-19." (PMID 34834450, 2021). "The presence or absence (insertion or deletion) of a 287-bp Alu sequence in the 16th intron of the ACE gene, which present on the 17th chromosome, has been strongly debated in terms of its association with the increased risk of diabetes and diabetic complications, myocardial infarction and HTN." (PMID 33507688, 2021). "From Round 5, the two topics on which CO-Search performs best, as ranked by Bpref, are “what kinds of complications related to COVID-19 are associated with diabetes” and “are patients taking Angiotensin-converting enzyme inhibitors (ACE) at increased risk for COVID-19?”." (PMID 33846532, 2021). "Diabetic patients are at especially high cardiovascular risk and the use of ACE-inhibitors and ARBs may help prevent diabetic nephropathy and other long-term complications of diabetes." (PMID 31656939, 2019). "Also the EUROPA and ADVANCE trials provided evidence that an ACE inhibitor treatment improved survival and reduced the risk of major cardiovascular events in patients with diabetes." (PMID 27652272, 2016).
diabetes (continued). "Conclusion—our study suggested that the ACE I/D polymorphism may contribute to DR development, especially in the Asian group with type 2 diabetes mellitus (T2DM)." (PMID 27854313, 2016). "The ACE I allele was found to be associated with diabetes among Kuwaitis." (PMID 27777603, 2016). "Thus, we have conducted a cross-sectional study to identify the association between obesity and ACE gene I/D polymorphism in Chinese patients with type 2 diabetes mellitus (T2DM)." (PMID 28115791, 2016). "In this retrospective cohort study conducted in 40,000 individuals with diabetes treated with either ACE inhibitors or ARBs, the risk of foot ulcer, and the risk of lower limb amputation for those with peripheral arterial disease were both twice higher for those on ACE inhibitors." (PMID 25888905, 2015). "The authors suggested that the ACE I/D polymorphism may contribute to nephropathy development, especially in the Asian group with type 2 diabetes mellitus." (PMID 25587546, 2014). "This study showed that diabetes was associated with increase of plasma ACE activity and this activity was decreased significantly by addition of formulation Om3/terp and this action probably resulted to omega-3 fatty acids existing in the fenugreek essential oil." (PMID 22142357, 2011). "Similar allelic and genotypic frequency of ACE I/D gene polymorphism was observed between healthy controls versus pooled type 2 diabetes mellitus (T2DM) subjects, and normoalbuminuria versus microalbuminuria, macroalbuminuria and End Stage Renal Failure (ESRF) (P > 0.05)." (PMID 21031056, 2010). "Our results add further strength to the existent recommendations to use ACE inhibitors in patients with congestive heart failure, diabetes mellitus, and renal disease, since these patients are at higher risk for either contracting pneumonia or dying from pneumonia when they do contract it." (PMID 16159398, 2005). "Previous studies indicate that both ACE inhibitors and ARBs may reduce the progression to type 2 diabetes in hypertensive patients; our study provides direct comparative evidence on their relative efficacy in improving IR - a key risk factor for diabetes." (PMID 40255834, 2025). "Finally, studies suggest that inhibition of the renin–angiotensin system, including ACE inhibitors and ARBs like valsartan, may reduce diabetes incidence and cardiovascular risk." (PMID 39543645, 2024). "The study is limited by the short duration of diabetes and the young age of the participants, which may influence the occurrence of DN and the non-significant association between the polymorphism of genes ACE, AGTR1, MTHFR, and DN." (PMID 39446857, 2024). "For instance, it is well established that the inhibition of amylase and glucosidase enzymes may reduce the postprandial glycemic index, which is linked to the development of diabetes, while inhibition of angiotensin-converting enzyme (ACE) may assist in maintaining normal blood pressure." (PMID 35631766, 2022). "However, angiotensin-converting-enzyme (ACE) inhibitors and angiotensin receptor blockers (ARBs) are favored by some investigators because of their ability to increase insulin sensitivity, thus diminishing the risk of diabetes mellitus." (PMID 26141622, 2015). "A number of studies have reported that patients suffering from proliferative retinopathy have high circulating levels of ACE, which implies that elevated serum ACE levels might be a possible risk factor in damaging retinal vascular apparatus in subjects suffering from diabetes." (PMID 26658948, 2015). "The effects of angiotensin-converting enzyme (ACE) inhibitors and angiotensin II receptor blockers (ARBs) on cardiovascular (CV) risk in hypertensive patients with type 2 diabetes mellitus (T2 DM) are uncertain." (PMID 25344747, 2014).
diabetes (continued). "The primary objective of the study was to find out pattern of distribution of ACE gene polymorphism in healthy controls, in patients of type II DM without nephropathy, in patients of type II DM with nephropathy and to study the relation between DD polymorphism and diabetes with nephropathy." (PMID 20535249, 2009). "Clinicians should prioritize BP control with antihypertensives like ACE inhibitors or ARBs, known to confer renal protection in patients with diabetes." (PMID 40734849, 2025). "The TG/HDL ratio was significantly associated with age, gender, smoking status, hypercholesterolemia, diabetes, and the chronic use of ACE inhibitors, statins, beta-blockers, aspirin, ADP antagonists, and diuretics." (PMID 40004901, 2025). "Third, critical variables including medication use (e.g., SGLT2i and ACE inhibitors), diabetes duration, and specific inflammatory biomarkers (e.g., hs-CRP) were not fully accounted for." (PMID 41255513, 2025). "Inhibited cyclooxygenase-2 (COX-2) and its product prostaglandin E (PGE), reduce the synthesis of IL-8, reduce intestinal inflammationEnhanced glucose transportation or inhibit gluconeogenesis.Inhibited the formation of ACE, alleviate diabetes complications." (PMID 41356003, 2025). "In diabetes, increased ACE activity elevates Angiotensin-II, through AT1 receptor activation, promotes oxidative stress, NF-κB–mediated inflammation, insulin resistance, and TGF-β–driven fibrosis." (PMID 41158128, 2025). "Many medicines used to treat diabetes (ACE inhibitors, angiotensin receptor blockers, ibuprofen, and thiazolidinediones) increase the secretion of ACE2." (PMID 39830837, 2025). "The model was adjusted for different parameters, such as age, sex, diabetes duration, HbA1c, blood pressure, use of ACE inhibitors, and diabetic retinopathy stages." (PMID 39857298, 2025). "DPP-IV inhibitor (BF = 0.6667): high potential inhibitory effect on DPP-IV, indicating potential benefits in metabolic regulation and diabetes control; ACE inhibitor (BF = 0.6000): high potential for cardiovascular protection through ACE inhibition." (PMID 40724906, 2025). "The kidney-protective effects of ACE inhibitors and ARBs also extend to patients with diabetes mellitus, particularly those with moderate-to-severe albuminuria." (PMID 41234923, 2025). "DPP-IV inhibitor (BF = 0.8182): the strongest DPP-IV inhibition among the analyzed peptides, suggesting a strong role in glucose metabolism and diabetes control; ACE inhibitor (BF = 0.1818): low potential in cardiovascular regulation." (PMID 40724906, 2025). "Previous data captured in the National Pregnancy in Diabetes Audit (NPID) 2020–2022 report a prescription rate of 4% for statins, 4% for ACE inhibitors, and 7% for adverse diabetes medications in women with type 2 diabetes who became pregnant." (PMID 40044453, 2025). "In cases of moderate to severe LVSD, those with diabetes were more likely to be started on ACE inhibitors/ARBs (81% vs 77%, p<0.001) and β-blockers (77% vs 74%, p<0.001) than those without diabetes." (PMID 39358593, 2024). "It was discovered that the use of lycopene effectively inhibited angiotensin-converting enzyme (ACE) activity, a crucial marker of problems associated with diabetes." (PMID 39519540, 2024). "The current study is the first to assess the correlations between the ACE I/D variant and the AGTR1 rs5182 polymorphism both independently and synergistically with diabetes mellitus in a Chinese elderly population." (PMID 39080710, 2024). "In children at risk of heart failure and early cardiovascular events, such as children with end-stage renal failure, diabetes, or congenital heart disease, ACE inhibitors are considered first line therapy." (PMID 38581464, 2024). "In contrast to this, individuals with diabetes in this study were more likely to be prescribed guideline-directed medical therapy such as β-blockers, ACE inhibitors and statins." (PMID 39358593, 2024).